TNF (tumor necrosis factor)
Diseases named in the same sentence as TNF in open-access papers (continued):
Sharing a sentence is not in itself a finding about the gene and the disease.
cancer (continued). "In particular, EwS EVs induced the release of IL-6, IL-8, and TNF by myeloid cells, consistent with similar findings in other cancers." (PMID 34440851, 2021). "TNFα signalling inhibition has been evaluated as a potential therapeutic strategy for cancer cachexia in clinical trials." (PMID 33414474, 2021). "This review provides an overview of the studies done in different stages of the TNF apoptosis-inducing ligands as cancer treatments and the strategies to surpass their natural limitations to improve their effectiveness." (PMID 33801589, 2021). "The resulting M2 macrophages can in turn promote cancer progression by releasing inflammatory mediators (including IL-6, tumor necrosis factor, interferon-γ, proteases, ROS, and nitrogen compounds)." (PMID 34074799, 2021). "Both TIL-iPS-T and TI-CTL slightly produced interferon-γ (INF-γ) and tumor necrosis factor (TNF), but hardly IL-2, in response to co-culturing with cancer spheroids." (PMID 34099861, 2021). "Given the mentioned pivotal role of TNFα in the immune system, another important concern regarding its blockade is related to cancer development." (PMID 33540543, 2021). "Allicin inhibited both gene and protein expression of TNF-alpha, IL-8, and endothelin in both cancer cells and cancer stem cells." (PMID 34071008, 2021). "By releasing TNF, interferon-γ, and other cytokines, lymphocytes can restrain cancer cell growth and metastasis." (PMID 32026332, 2021). "The majority of cancer-related pathways were upregulated, including the TNF signalling pathways, Estrogen signalling, and MAPK signalling pathways, and the cell cycle pathway was downregulated." (PMID 34885166, 2021). "Lim and coworkers report that tumor necrosis factor-alpha (TNF-α) is a pivotal transducer of cancer cell-mediated suppression of Tc cell surveillance through the stabilization of PD-L1." (PMID 34575998, 2021). "Fifteen important signaling pathways were screened, such as the cancer pathway, TNF signaling pathway, PI3K-AKT signaling pathway, HIF-1 signaling pathway, and Toll-like receptor signaling pathway." (PMID 34660782, 2021). "Tumor necrosis factor (TNF)-related apoptosis-inducing ligand (TRAIL) is a promising anti-cancer agent that belongs to the TNF superfamily." (PMID 35140606, 2021). "TNF-α, as a biomarker in lung cancer patients, has an established involvement in inflammation and also plays a key role in inflammation-induced cancer in vitro and in vivo." (PMID 34833849, 2021). "This phenolic compound inhibits the COP9 signalosome 5 (CSN5), which is required for tumor necrosis factor-alpha (TNF-α)-mediated PD-L1 stabilization in cancer cells." (PMID 33572626, 2021). "TNFRSF19 belongs to the tumor necrosis factor (TNF) receptor superfamily and it has been identified that the up-regulation of TNFRSF19 is associated with poor outcomes in various types of cancer 45-47." (PMID 33437203, 2021). "KEGG analysis showed the differentiated proteins mainly correlated with pathways in cancer, chemokine pathway and TNF pathway." (PMID 34526098, 2021). "In the following sections, we briefly report the results of two case studies: the anti-cancer effects of metformin and the testing TNFα/siTPL2-dependent synthetic lethality on a subset of human cancer cell lines." (PMID 34166365, 2021). "KEGG enrichment analysis of differentially expressed showed that LINC01559 or UNC5B-AS1 knockdown contributed to alterations in several signaling pathways, such as TNF signaling pathway, IL-17 signaling pathway, and transcriptional misregulation in cancer." (PMID 33390837, 2021).
cancer (continued). "Such destabilization of lysosomes specifically occurs in cancer cells, followed by the release of lysosomal enzymes, including Cathepsin B and Cathepsin D. Cathepsin B mainly contributes to TNF‐α‐induced necrosis, while Cathepsin D evokes apoptosis." (PMID 34523247, 2021). "In most types of cancer cells, the dominant outcome is cell survival, and thus resistant to TNF-α-induced apoptosis." (PMID 33633307, 2021). "Although preclinical data of TNF-α treatment in cancers to improve drug delivery is promising, the treatment efficacy in cancers is not known due to the lack of phase II clinical trials." (PMID 33986746, 2021). "XIAP overexpression in cell lines and cancer tissues has been revealed to inhibit apoptosis stimulated by a variety of apoptotic stimuli, including Fas, tumor necrosis factor, withdrawal of serum or growth factor, and radiation therapy." (PMID 34712428, 2021). "Subsequent ELISA analysis indicated that PBMF evidently diminished the serum level of TNF-α, which is a common anti-neoplastic cytokine that can induce directly the necrosis of cancer cells." (PMID 33964908, 2021). "INF-γ and TNFα produced by CD8+ cytotoxic T lymphocyte (CTL) contribute to CTL-derived cytotoxicity to cancer cells." (PMID 34945007, 2021). "TNF-α is considered to be a potential therapeutic drug for cancer, but the systemic toxicity problem still exists in clinical use." (PMID 34356509, 2021). "A current important area of investigation is how TNF in tumors and TNF in the microenvironment of tumors influences the biology of cancers." (PMID 33373873, 2021). "Both cytokines (IFN-γ and TNF) play pivotal regulatory roles in cellular homeostasis, immune response, and cancer progression." (PMID 34947825, 2021). "This is reflected by our data: ASTX660/birinapant plus TRAIL is superior to ASTX660/birinapant plus TNF in cancer cell killing." (PMID 33484626, 2021). "Inflammatory mediators such as TGF-β and IL-6 have been reported to aid the metastasis and invasion of cancer cells 53, TNF-α mediates the transition from chronic inflammation to cancer by acting as a master switch." (PMID 34345201, 2021). "Recent studies are pointing out the pleiotropic role of TNF-alpha in cancer development and progression." (PMID 34283046, 2021). "Previous studies have shown that TNF-α alters the redox status, and in turn activates NF-κB in cancer cells." (PMID 33816268, 2021). "In relation to cancer biology, TNF was initially reported as a serum factor that induced necrosis of tumors." (PMID 33373873, 2021). "NK cells can secrete a number of cytokines and growth factors, including interferon-γ (IFN-γ), TNF-α, and granulocyte–macrophage colony-stimulating factor (GM-CSF) to kill cancer cells." (PMID 33752691, 2021). "Adiponectin has anticarcinogenic effects by directly inhibiting tumor necrosis factor-α (TNF-α) and stopping the activation of cancer cell caspase." (PMID 34259747, 2021). "It has been shown that cytokines, especially IL-6, IL-18 and TNFα, are involved in both inflammaging and different chronic conditions such as heart disease, kidney disease and cancer." (PMID 34444668, 2021). "To investigate the therapeutic effect of TNFα antagonism in cancer pain we used two cancer models, treated the animals with a TNFα neutralizing compound C-8722, and measured nociceptive behavior." (PMID 33469141, 2021). "Treatment of cancer cells with ilexgenin A reduces cell viability and mRNA levels of β-catenin and TNF, suggesting that ilexgenin A acts by disturbing multiple signaling events." (PMID 34575983, 2021). "TNF-induced apoptosis in cancer cells can also be increased by overexpressing the inhibitor of NFκB such as IκB, or by co-administration of selective NFκB inhibitor." (PMID 34025421, 2021). "TNF-α is also characterized by an imbalance between survival and apoptosis signals in many pathological situations, including cancer." (PMID 33816268, 2021).
cancer (continued). "MMP-2 is an enzyme-degrading type IV collagenase that stimulates the secretion of active MMP-2 by TNF-α and activates processes involved in wound healing and cancer cell invasion." (PMID 33917793, 2021). "The carcinogenic mechanism of inflammation linked to TGF-β or TNF-α and its regulation of ARRB1 in GBC or other cancers still needs to be fully elucidated." (PMID 33753990, 2021). "Further assessment of macrophage function revealed that exogenous TNF‐α increased cancer cell migration and PI3Kα inhibition impaired TNF‐α‐mediated migration." (PMID 34057823, 2021). "Conversely, CTLs indirectly target cancer cells via the secretion of cytokines, namely TNF-α and IFNγ, and the activation of cytotoxic macrophages and neutrophils." (PMID 34685635, 2021). "KEGG pathway enrichment analysis results show that lotus leaf can play a weight loss effect through the hypoxia-inducible factor-1 (HIF-1) signaling pathway, tumor necrosis factor (TNF) signaling pathway, and multiple signaling pathways related to cancer." (PMID 34745273, 2021). "Tumor necrosis factor (TNF) is a multifunctional inflammatory cytokine that has both pro-tumorigenic and anti-tumorigenic roles in human cancers." (PMID 34771644, 2021). "Several cytokines such as IL-6, IL-10, TGF-β, TNF-α, and Nodal can regulate the chemoresistance of cancer cells." (PMID 33754002, 2021). "In the context of TLS neogenesis, M1 macrophages can produce chemokines similar to those detected in TLS+ human cancers, including Ccl21 and TNFα." (PMID 34122434, 2021). "The inflammatory response from cancer cells promotes the infiltration of neutrophils, which benefits cancer progression via the secretion of IL-2, IL-6, IL-10, TNFα, and VEGF." (PMID 34503128, 2021). "Considering the inter-triggering mechanism of cancer progression and inflammation, we assessed the production of pro-inflammatory cytokines, including IL-6, TNF-α, and IFN-γ, and the anti-inflammatory cytokine IL-10 in CAC mice in colon tissue and serum." (PMID 33996624, 2021). "KEGG pathway analysis suggests that PLAU and PLAUR are mainly involved in the proteoglycan-related cancer signaling pathway, Wnt signaling pathway, and TNF signaling pathway." (PMID 35087738, 2021). "Contrarily to the well-known activity of CTA, the role of TNF-dependent immune response in cancer progression is contradictory." (PMID 34968251, 2021). "We have also discussed potential biomarkers involved in pathways that are differentially affected or modified during the onset of HPV-related cancers, such as Akt, mTOR, miRNAs, TNF-α, TGF-β, BRCA1, and FANCD2." (PMID 33668730, 2021). "IL6 and TNF α are inflammatory cytokines that also have direct cytotoxic effects on cancer cell lines and are able to recruit immune cells." (PMID 34944584, 2021). "Due to its wide-ranging functions, TNF-α is also responsible for divergent actions in the context of cancer through its two receptors." (PMID 34712661, 2021). "TNFα is an inflammatory cytokine secreted by the inflammatory cells and adipocytes as well as cancer cells." (PMID 33799622, 2021). "TB reactivation is an established adverse effect attributed to many anti-cancer biological agents and with TNF-α inhibitors as well." (PMID 33070259, 2021). "It has been found that the seven-gene panel interacted with major inflammatory and cancer signaling hallmarks including TNF, PI3K, NF-κB, and TGF-β." (PMID 35008645, 2021). "Combinatorial treatment strategies with SM and exogenously added TNF (or other death‐inducing ligands from the TNF super family such as TRAIL) overcome SM resistance in various cancer entities." (PMID 33484626, 2021). "p65 O-GlcNAcylation at Thr-322 and Thr-352 also enhances DNA binding to the promoters of IL-6, TNF-α, and MCP1 which contributes to the development of colitis and colitis-associated cancer." (PMID 34722537, 2021).
cancer (continued). "GSDMC is cleaved by caspase-8 with TNFα treatment, and also can be cleaved by caspase-6 in response to reactive oxygen species (ROS) insult in cancer cells." (PMID 34421915, 2021). "On the other hand, in an attempt to control the tumorigenesis process, CD4+ T-regulatory cells secrete TNF-α, a molecule that shows a dual role in immunomodulation, being also expressed by cancer cells, acting as an autocrine growth factor." (PMID 33644151, 2021). "Anti-TNF agents are in clinical use for cancer treatment but due to the systemic dose related toxicity, a recombinant NGR–TNF fusion protein was developed." (PMID 33918106, 2021). "Fortunately, group 3 includes three important pathways involved in the pro-inflammatory and metastasis process, IL−17 signaling pathway, TNF signaling pathway, and Transcriptional misregulation in cancer." (PMID 34490085, 2021). "KEGG pathway analysis defined the most significantly enriched pathways of the epigenetically-regulated genes, were found to be enriched in ‘TNF signaling pathway’, ‘Proteoglycans in cancer,’ and ‘Pathways in cancer’." (PMID 34136486, 2021). "We found that T cell-derived TNFα can synergize with chemotherapy to intensify oxidative stress in cancer cells in a NOX-dependent manner." (PMID 33673398, 2021). "Unfortunately, systematic treatment of TNF leads to severe toxicity, making it less likely to be used as a cancer therapeutic." (PMID 33717106, 2021). "Of note, a small number of them (12 on thiopurines and 3 on anti TNF-alpha drugs) maintained their immunosuppressive therapy through their cancer treatment." (PMID 33540674, 2021). "Immune response against malignant tumors can also be achieved indirectly through secretion of various cytokines, e.g., tumor necrosis factor (TNF) alpha or interferon gamma." (PMID 34830233, 2021). "It has been reported that inflammatory cytokines such as interleukin-6 (IL-6) and tumor necrosis factor alpha (TNF-α) in the TME are able to enhance PD-L1 expression in cancer cells, contributing to escape from T cell immune surveillance." (PMID 33514004, 2021). "A plethora of literature has implicated the functional role of TNF-α and TNF-β in promoting cancer development through autocrine and paracrine signal transduction involved in cancer cell proliferation, invasion, and metastasis even in CRC." (PMID 34660256, 2021). "In cancer cachexia, tumor-derived factors such as IL-6 and TNF-α are key drivers of lipolysis and fat depletion." (PMID 34627306, 2021). "They found that administration of curcumin (30 μM) in coculture with CAFs and cancer cells suppressed TNF-α signalling and survival pathways." (PMID 34834295, 2021). "Multiple cancer phenotypes were significantly enriched for conserved, pan-cell type, and top-ranked pre-TNFα RELA peak categories." (PMID 33495464, 2021). "The main focus has been on tumor necrosis factor (TNF)-related apoptosis-inducing ligand (TRAIL)-based cancer therapy, TNF-α and TRAIL being major mediators of death receptor-mediated apoptosis." (PMID 33761944, 2021). "The TIMER database is a web resource used for systemic analysis and evaluation of clinical impacts of different immune factors in diverse cancer types hence we analyzed the correlation between TNF-α and the expression level of identified DEPs." (PMID 33926547, 2021). "Both TNFα and TGFβ have been shown to induce transcription factors such as Snail and Twist in immune cells and cancer cells." (PMID 33826645, 2021). "PPAR γ agonists, including the thiazolidinedione derivatives rosiglitazone, pioglitazone, and troglitazone, attenuate cancer-induced body weight wasting and TNF-α-induced adipocyte wasting." (PMID 34502316, 2021). "Other cancer randomized controlled trials have observed a significant reduction of TNF serum levels after 12 weeks of HBE." (PMID 33613573, 2021). "In the ovarian organoid model, prolonged TNF exposure confers precancerous phenotypes with high expression of cancer markers." (PMID 34307156, 2021).
cancer (continued). "Succinctly, BAs stimulate/decrease the secretion of inflammatory factors such as IL-6 and TNF-α on the one hand, thereby activating/inactivating signal pathways related to cancer promotion to improve/inhibit cancer growth or invasiveness." (PMID 35127481, 2021). "Vascular disruption leading to the reduction in intratumoral IFP is the key concept behind the therapeutic uses of TNF-α to improve drug delivery efficiency in cancer treatments." (PMID 33986746, 2021). "AC022509.2 is related to “NF-kappa B signaling pathway”, “TNF signaling pathway”, “Apoptosis”, and “PD-L1 expression and PD-1 checkpoint pathway in cancer”." (PMID 34094983, 2021). "JAK-STAT signaling and TNF signaling pathways are major mediators of apoptosis as well as inflammation and immunity in many cancers." (PMID 33416081, 2021). "KEGG pathway analyses showed five significant pathways associated with the inflammatory and metastasis processes in cancer, which include the TNF, IL−17, NF-kappa B, MAPK signaling pathways, and transcriptional misregulation in cancer." (PMID 34490085, 2021). "The current study indicates PGG potential as an anti-cancer compound, inhibiting the expression of TNFα-induced CXCL1 via inhibition of the expression of genes and proteins involved in the NFқB and MAPK signaling in MM-231 and MM-468 TNBC cell lines." (PMID 33707603, 2021). "The stabilization of PD-L1 results in tumor necrosis factor-alpha (TNF-α)-triggered cancer cell immune escape from T cell surveillance." (PMID 34829931, 2021). "The distinct and opposing effects of TNFα in cancer depend on cytokine concentration and s- TNFα or tm- TNFα isoforms, distinct caspase activation, varied expression of adaptor proteins, different expression levels of members of the Bcl-2 family, among others." (PMID 33540543, 2021). "The inflammatory cytokines including interleukins and tumor necrosis factor-alpha play a significant role in many disease conditions including cancer." (PMID 34122114, 2021). "MDSC-secreted factors that overlap with TREM-1 target genes, including IL-1β, TNF-α, IL-8 and IL-6, have been reported to promote angiogenesis and induce cancer cell migration, invasion, and survival." (PMID 34956864, 2021). "We demonstrated that markedly higher serum IL-6 levels in cancer patients compared to healthy control individuals and a positive correlation between the serum IL-6 levels with the TNF-α and NF-κB levels." (PMID 33776564, 2021). "These genes were enriched in the inflammatory response, cellular response to mechanical stimulus, TNF signaling pathway, and cancer-related pathways." (PMID 35087950, 2021). "Th1 cytokines IFN-γ and TNF-α have been known to induce apoptosis and senescence in various cancer cell lines while suppressing the expression of a number of growth factor receptors such as HER-2 and HER-3." (PMID 33936816, 2021). "Although we demonstrated the safety of gold nanomedicine carrying TNF-α in humans, the anti-cancer efficacy was limited, with only a partial response in 27 evaluable participants with advanced solid cancers." (PMID 33986746, 2021). "TNF-α and IL-6 are well-known cytokines that provoke cancer cachexia in the C26 adenocarcinoma model, where we measured the serum levels of both." (PMID 34262449, 2021). "The inflammatory cytokine TNF-alpha is responsible for acute inflammation and signalling that initiates necrosis or apoptosis with importance during resistance of infections and cancer development." (PMID 35008824, 2021). "With this enhanced plasmonic effect, the detection limit has been experimentally demonstrated to be 10–15 mol L−1 for TNF-α cancer marker, which has been found in various human diseases including inflammatory diseases and different kinds of cancer." (PMID 34138312, 2021). "Comprehensively, the data presented in this section point to the central role of TNFα in cancer initiation, progression, and metastasis, despite its potential to activate cell death when present in high concentrations." (PMID 33540543, 2021).